RNU1-78P (RNA, U1 small nuclear 78, pseudogene)
Gene: Small nuclear RNA gene on chromosome 15 (45,002,864 to 45,003,028, reverse strand). Ensembl gene ENSG00000212550.
Homologues: Orthologues: chimpanzee U1 (98% identical), macaque U1 (91% identical), macaque U1 (88% identical). Paralogues in human: RNU1-119P (99% identical), RNU1-89P (90% identical), RNU1-1 (88% identical), RNU1-2 (88% identical), RNU1-27P (88% identical), RNU1-28P (88% identical), RNU1-3 (88% identical), RNU1-4 (88% identical), RNU1-83P (88% identical), RNVU1-18 (88% identical), RNVU1-29 (88% identical), U1 (88% identical), and 134 more.